BACE1 (beta-secretase 1)
Diseases named in the same sentence as BACE1 in open-access papers (continued):
Sharing a sentence is not in itself a finding about the gene and the disease.
colon cancer (2 papers, 2012 to 2024). "In colon cancer cells, IR increased the expression of BACE1, which is involved in IR-mediated cleavage of ST6Gal I." (PMID 22449099, 2012). "Elevated expression of PRNP in homozygous mice was accompanied by increased expression of a set of genes that we previously identified as PrPC gene targets in colon cancer cells, namely App, Bace1, Dkk3, Pdgfc and Tgfb1, thus validating our model as a robust PRNP-overexpressing paradigm." (PMID 38589873, 2024). "Importantly, IR (10 Gy) increased the expression of BACE1 at both mRNA and protein levels in SW480 and CT26 colon cancer cell lines." (PMID 22449099, 2012).
colorectal cancer (2 papers, 2019 to 2022). A primary or metastatic malignant neoplasm that affects the colon or rectum. "ROC curve analysis indicated sensitivity and specificity in LINC-PINT and BACE1 for colorectal cancer diagnosis." (PMID 36087249, 2022). "In this study, there was a significant correlation between the level of expression of BACE1 and lymph node involvement in patients with colorectal cancer." (PMID 36087249, 2022). "In this study, we have shown a new link between lymph node involvement in patients with colorectal cancer and the levels of LINC-PINT and BACE1 mRNA expression in CRC tumour samples." (PMID 36087249, 2022).
endothelial dysfunction (2 papers, 2017 to 2018). In vascular diseases, endothelial dysfunction is a systemic pathological state of the endothelium (the inner lining of blood vessels) and can be broadly defined as an imbalance between vasodilating and vasoconstricting substances produced by (or acting on) the endothelium. "We found that BACE1 upregulation in TNFα-treated endothelial cells leads to ST6Gal-I proteolysis and results in endothelial dysfunction and monocyte-endothelial cell adhesion." (PMID 28091531, 2017). "BACE1 inhibition markedly inhibited TNFα-induced endothelial dysfunction and monocyte adhesion." (PMID 28091531, 2017). "Notably, inhibition of BACE1 has beneficial effects on senescence induced endothelial dysfunction." (PMID 29348391, 2018).
epileptic seizures (2 papers, 2023 to 2024). "Here we show that BACE1 inhibition actually reduces sleep disturbances and epileptic seizures; both are seen in AD patients." (PMID 37536983, 2023). "Since eIF2a and eIF4B phosphorylation positively regulate BACE1 mRNA levels and PERK-mediated phosphorylation of eIF2a is induced in TLE, epileptic seizures might increase BACE1 mRNA levels via eIF2a phosphorylation." (PMID 39545066, 2024).
Impaired glucose tolerance (2 papers, 2018 to 2025). An abnormal resistance to glucose, i.e., a reduction in the ability to maintain glucose levels in the blood stream within normal limits following oral or intravenous administration of glucose. "Similar regulation of plasma IRsol levels, liver IR and BACE1 mRNA levels, and protein amounts was observed in high-fat diet (HFD) fed mice with impaired glucose tolerance, compared with normal-fat diet fed mice." (PMID 29610518, 2018).
lysosomal disorder (2 papers, 2016 to 2018). "In this work, we employed a single gene lysosomal disorder of cholesterol accumulation—NPC, which was previously shown to share several similarities with complex AD, to further characterize proteolysis carried out by BACE1." (PMID 29979789, 2018).
multiple sclerosis (2 papers, 2010 to 2012). A progressive autoimmune disorder affecting the central nervous system resulting in demyelination. "BACE-1 is highly expressed at the time when peripheral nerves become myelinated and is needed for neuregulin processing, with loss of BACE-1 inducing hypomyelination, suggestive of a role for IL-18 and BACE-1 in multiple sclerosis." (PMID 22898493, 2012).
Neurodegeneration (2 papers, 2016 to 2021). Progressive loss of neural cells and tissue. "Other than the potential candidate genes, the compact SPNW also included many significant connecting proteins like APP, BACE1, CCNA2, CREB1, E2F1, EGR1 and MDM2 which were previously implicated to play critical roles in many neurodegeneration disease pathogenesis including Alzheimer’s." (PMID 26784894, 2016).
periodontitis (2 papers, 2021 to 2023). An acute or chronic inflammatory process that affects the tissues that surround and support the teeth. "Upregulation of APP and its homologs, as well as BACE1 and PS could be found in the present study, indicating that ligature-induced periodontitis could modulate APP processing through enhanced β- and γ-site secretase activity." (PMID 33757547, 2021).
prion disease (2 papers, 2012). A transmissible disease that is caused by a protein that is able to induce abnormal folding of normal cellular proteins, leading to characteristic spongiform brain changes, which are associated with neuronal loss without an inflammatory response. "The effect of BACE1 polymorphism appears to be age-dependent, being more relevant in earlier onset sCJD patients, where a genetic interaction is observed between BACE1 and the major susceptibility marker for human prion diseases (PRNP)." (PMID 22952813, 2012). "However, as the processing of APP by BACE1 is a key step for the production of Aβ peptides, and AICD in turn up-regulates PrP expression, increased levels of BACE1 could be related to higher cellular levels of PrP that are associated with increased susceptibility to prion diseases." (PMID 22952813, 2012). "It was found that human prion disease-associated mutations in PrPC did not inhibit BACE1, and scrapie infected mice brains contained dramatically higher Aβ levels, suggesting a loss of PrPC function perhaps as a result of PrPC-PrPSc conversion during prion disease progression." (PMID 22363722, 2012).
proteinopathies (2 papers, 2024). "This perspective aims to highlight recent PET radiotracers developed for five emerging targets in proteinopathies (i.e., mHTT, BACE1, TDP-43, OGA, and CH24H)." (PMID 39185440, 2024).
temporal lobe epilepsy (2 papers, 2012 to 2021). A localization-related (focal) form of epilepsy characterized by recurrent seizures that arise from foci within the temporal lobe, most commonly from its mesial aspect. "Alternatively, the elevated BACE1 expression might occur as a part of intrinsic modulation of altered synaptic/axonal plasticity, a pathological hallmark of temporal lobe epilepsy." (PMID 23155407, 2012). "Notably, BACE1 elevation and colocalization with PSA-NCAM are associated with aberrant limbic axonal sprouting in a model of temporal lobe epilepsy." (PMID 33548223, 2021).
Thiamine deficiency (2 papers, 2017 to 2023). Thiamine deficiency is a condition that occurs due to not enough thiamine (vitamin B1). "Additionally, in a low metabolic state due to thiamine deficiency, BACE1 activity increases and results in more Aβ production." (PMID 36834911, 2023). "Similar lack of energy metabolism is seen in thiamine deficiency, which causes an increase in BACE1 activity and Aβ accumulation." (PMID 36834911, 2023). "Similarly, thiamine deficiency, which leads to neuronal death, activates the PKR-eIF2α pathway and increases the BACE1 expression levels of Aβ in specific thalamus nuclei." (PMID 29170442, 2017).
viral infection (2 papers, 2015 to 2021). "Recent studies have indicated that activated eIF2α increases BACE1 translation under specific conditions, such as energy deprivation, oxidative stress and viral infection, although eIF2α activation generally elicits translational attenuation." (PMID 26552445, 2015).
absence seizures (1 paper, 2010). "Apart from absence seizures, BACE1-/- mice also demonstrate more severe seizures and hippocampal injury following administration of KA, suggesting that abnormal excitability is not restricted to neurons involved in thalamocortical pathways." (PMID 20731874, 2010).
acute pancreatitis (1 paper, 2015). An acute inflammatory process that leads to necrosis of the pancreatic parenchyma. "To address, if a loss of Bace1 leads to an increased severity of acute pancreatitis, we induced pancreatitis in Bace1-/- mice by intraperitoneal caerulein-injections." (PMID 25961820, 2015). "Based on these observations, we proposed an involvement of BACE1 in a defense mechanism during development of acute pancreatitis." (PMID 25961820, 2015). "Based on these findings, we postulated a possible protective function of Bace1 against the development of acute pancreatitis by counteracting premature trypsinogen activation via enteropeptidase." (PMID 25961820, 2015). "In vitro experiments revealed enteropeptidase as a putative substrate for Bace1 suggesting a role in acute pancreatitis." (PMID 25961820, 2015). "Based on our previous findings, we proposed a possible protective function of BACE1 in the pathogenesis of acute pancreatitis." (PMID 25961820, 2015). "To address this hypothesis, we induced acute pancreatitis in homozygote Bace1-/- and wild type mice by intraperitoneal injection of caerulein." (PMID 25961820, 2015).
alcoholic liver diseases (1 paper, 2024). A disorder caused by damage to the liver parenchyma due to alcohol consumption. "A reduced UCHL1 activity is related to increased BACE1 and Aβ peptide accumulation in the brain; UCHL1 was found to be upregulated in hepatic stellate cells upon activation in fibrosis, as well as in samples from patients with alcoholic liver disease." (PMID 39201455, 2024).
astrocytoma (1 paper, 2015). "Recently, it was reported that Aβ induces BACE1 expression in primary astrocytes as well as in human astrocytoma cell line." (PMID 25773675, 2015).
autism spectrum disorder (1 paper, 2020). A spectrum of developmental disorders that includes autism, and Asperger syndrome. "Hsa-mir-328 has been reported to be associated with a variety of neurologic disorders, such as autism spectrum disorder, Huntington’s, Parkinson’s, and Alzheimer’s, and the biological functions of its targeting genes APP and BACE1 were validated experimentally in mouse brain tissues." (PMID 32154224, 2020).
autoimmune disease (1 paper, 2025). A disorder resulting from loss of function or tissue destruction of an organ or multiple organs, arising from humoral or cellular immune responses of the individual to their own tissue constituents. "Although the direct relationship between BACE1 and SLE has not been extensively studied, the broad effects of BACE1 on immune function and cellular signaling pathways imply a potential intersection with autoimmune diseases such as SLE." (PMID 39823480, 2025).
bipolar disorder (1 paper, 2020). A disorder of the brain that causes unusual shifts in mood, energy, activity levels and the ability to carry out day-to-day tasks. "Indeed, in a study conducted in patients suffering from bipolar disorder, a sex-based dimorphism in BACE1 gene expression levels was reported, with men displaying upregulation of BACE1 expression." (PMID 33066807, 2020).
bladder cancer (1 paper, 2018). "Little is known about the association between BACE1 and cancer; however, because bladder cancer exhibits the highest median age (i.e., 73 years) at diagnosis of all cancer types, this gene may have an association with disease development in aging populations." (PMID 29300757, 2018).
Blindness (1 paper, 2022). Blindness is the condition of lacking visual perception defined as a profound reduction in visual perception. "The specificity of VHH‐B9 for BACE1 also avoids issues of impaired glucose homeostasis, hypopigmentation, seizures, and blindness (among others), which are associated with cross‐reactivity with BACE2, Cathepsin D, and Cathepsin E." (PMID 35352880, 2022).
cardiac arrhythmia (1 paper, 2019). Any disturbances of the normal rhythmic beating of the heart or MYOCARDIAL CONTRACTION. "Aside from BACE2 inhibition, the only other significant off-target (non-BACE1) activity of verubecestat is the inhibition of the hERG channel which is a common cause of QTC prolongation and cardiac arrhythmias." (PMID 31387606, 2019).
choroidal neovascularization (1 paper, 2012). An eye disorder described by the growth of new blood vessels that originate from the choroid through a break in the Bruch membrane into the sub–retinal pigment epithelium (sub-RPE) or subretinal space. "The effect of BACE1 inhibition on in vitro angiogenesis is recapitulated in vivo using the laser-induced model of choroidal neovascularization (CNV)." (PMID 22903875, 2012).
Cirrhosis (1 paper, 2020). A chronic disorder of the liver in which liver tissue becomes scarred and is partially replaced by regenerative nodules and fibrotic tissue resulting in loss of liver function. "During cirrhosis, the decreased expression of APP and its cleaving enzymes BACE1 and PS1, which are regulated by NO, results in a dramatic intrahepatic decrease of Aβ." (PMID 32089540, 2020). "In view of the capacity of NEP to degrade Aβ, its upregulation in the BDL model of cirrhosis may exaggerate injury already promoted by low levels of PS1 and BACE1." (PMID 32089540, 2020).
colitis (1 paper, 2025). Inflammation of the colon. "Further, APP processing or the levels of BACE1 and beta‐amyloid degrading enzymes were altered by acute colitis." (PMID 40457749, 2025).
convulsion (1 paper, 2010). A rapid and repeated body muscle contract that results in an uncontrolled shaking of the body. "After convulsions, BACE1-/- mice showed decreased movement and attenuated EEG amplitude lasting 1-2 minutes." (PMID 20731874, 2010).
Creutzfeldt-Jakob Disease (1 paper, 2012). "Provided that common pathophysiologic mechanisms are shared by Alzheimer’s and Creutzfeldt-Jakob (CJD) diseases, we investigated for the first time to the best of our knowledge a possible association of a common synonymous BACE1 polymorphism (rs638405) with sporadic CJD (sCJD)." (PMID 22952813, 2012).
Crohn disease (1 paper, 2023). A gastrointestinal disorder characterized by chronic inflammation involving all layers of the intestinal wall, noncaseating granulomas affecting the intestinal wall and regional lymph nodes, and transmural fibrosis. "In a previous study, BACE1 was pointed out to mediate the progression of Crohn’s disease by regulating cuproptosis." (PMID 37090740, 2023).
delirium (1 paper, 2020). A disorder characterized by confusion; inattentiveness; disorientation; illusions; hallucinations; agitation; and in some instances autonomic nervous system overactivity. "However, there was no direct research showing that BACE1 is associated with delirium currently." (PMID 33192455, 2020).
folic acid deficiency (1 paper, 2016). "In a previous study we have revealed folic acid deficiency down-regulated miR-339-5p, which targets BACE1." (PMID 27618097, 2016).
generalized tonic-clonic seizures (1 paper, 2010). "Interestingly, all of the generalized tonic-clonic seizures in BACE1-/- mice began during non-REM sleep, and were characterized by an abrupt loss of muscle tone (atonia) lasting 2-3 seconds, followed immediately by tonic-clonic convulsions lasting from 1-4 minutes." (PMID 20731874, 2010).
Glucose intolerance (1 paper, 2016). Glucose intolerance (GI) can be defined as dysglycemia that comprises both prediabetes and diabetes. "Physiological and molecular analyses demonstrated that centrally expressed human BACE1 induced systemic glucose intolerance in mice from 4 months of age onward, alongside a fatty liver phenotype and impaired hepatic glycogen storage." (PMID 27138913, 2016).
hematoma (1 paper, 2023). A hematoma is a collection of blood from a vascular structure into an extravascular space. "Collectively, this study shows that microglial BACE1 is a promising approach to promote functional recovery after ICH and elucidates the underlying mechanism of neuroinflammation and hematoma resolution." (PMID 37552127, 2023). "Inhibition of either BACE1 or STAT3 alleviated adverse neuroinflammation and enhanced anti-inflammatory function and hematoma resolution in experimental ICH." (PMID 37552127, 2023). "Importantly, we found that BACE1 is upregulated in microglia in the early phase of ICH, when there is abundant neuroinflammation, persistent hematoma compression, and blood-brain barrier disruption." (PMID 37552127, 2023).
Hepatic steatosis (1 paper, 2024). Steatosis is a term used to denote lipid accumulation within hepatocytes. "Additionally, we found unchanged BACE1 mRNA in vitro, but a reduced BACE1 protein expression in the livers of HFD mice, which might be due to increased Nrf2 (nuclear factor erythroid-derived 2-related factor 2, NFE2L2) activity under oxidative stress in hepatic steatosis." (PMID 39201455, 2024).
hyperhomocysteinemia (1 paper, 2025). A serious metabolic condition caused by mutations in the MTHFR gene, medications, or nutritional deficiency. "Liraglutide reduces APP expression and phosphorylation, BACE1 and PSEN1, and increases α-secretase in hyperhomocysteinemia and AlCl3-induced AD." (PMID 41146261, 2025).
insulinoma (1 paper, 2020). "Indeed, BACE1−/− mice show impaired insulin expression in the pancreas and siRNA-mediated BACE1 knockdown significantly reduces insulin mRNA and protein in insulinoma cells." (PMID 32728795, 2020).
Intellectual disability (1 paper, 2023). "Finally, the significant effects obtained relative to DYRK1A and BACE1/C99 represent promising observations in searching for new molecules for ameliorating intellectual disability and fighting AD development in DS." (PMID 36670973, 2023).
liver cirrhosis (1 paper, 2021). "In human liver cirrhosis, beta-secretase 1 and neprilysin, which efficiently degrades the Aβ peptides, were suppressed, suggesting that production and degradation pathways were downregulated." (PMID 34204545, 2021).
lung carcinoma (1 paper, 2025). "Nevertheless, our data are supportive of targeting BACE1 in KRAS driven lung cancers which also have a strong predilection to end up in the brain." (PMID 40601773, 2025). "Importantly, BACE1 expression was elevated in our BMIC signature derived from disseminated lung cancer cells in the brain." (PMID 40601773, 2025). "However, since our screen was conducted with these models and identified the cell autonomous role of BACE1 in the development of lung cancer brain metastasis, these findings are likely to be conserved in the presence of immune cell populations." (PMID 40601773, 2025).
lung squamous cell carcinomas (1 paper, 2025). "To evaluate whether BACE1 expression is clinically relevant in NSCLC, we stained a NSCLC tumor microarray (TMA) consisting of primary LUAD and lung squamous cell carcinomas (LUSC; fig." (PMID 40601773, 2025).
lymphoid cancer (1 paper, 2024). "RNAi (Achilles + DRIVE + Marcotte, DEMETER2) showed that hematopoietic and lymphoid cancer cells are dependent on BACE1 expression." (PMID 38248330, 2024).
metastatic melanoma (1 paper, 2020). A melanoma that has spread from its primary site to another anatomic site. "Knowing that BACE1 and BACE2 are both involved in amyloid processing, we hypothesized that BACE2 should be mainly responsible for amyloid maturation in metastatic melanoma as it is more expressed in metastatic compared to primitive cells, while BACE1 shows an opposite behavior (Fig EV4B)." (PMID 32749065, 2020).
microcephaly (1 paper, 2024). A congenital or acquired developmental disorder in which the circumference of the head is smaller than normal for the person's age and sex. "Degradation by the β-site APP cleavage enzyme (BACE1) via the amyloidogenic pathway results in the secretion of AICD and amyloid beta (Aβ), which is potentially associated with psychiatric symptoms and microcephaly in AD and ASD." (PMID 39457485, 2024).
migraine (1 paper, 2011). "Further, rs1047964 in BACE1 appeared to be associated with CVD death among women with any migraine (OR = 4.67; 95% CI 2.53–8.62; p = 8.0×10−7)." (PMID 21779381, 2011).